CD4 (CD4 molecule)
Diseases named in the same sentence as CD4 in open-access papers (continued):
Sharing a sentence is not in itself a finding about the gene and the disease.
schizophrenia (continued). "In schizophrenia, increased numbers of natural killer (NK) cells, naive B cells, CXCR5 memory cells, and classical monocytes have been demonstrated and decreased numbers of dendritic cells (DCs), HLA-DR+ regulatory T cells (Treg), and CD4+ memory cells have been demonstrated." (PMID 39596417, 2024). "Furthermore, the mitochondrial lymphocyte counts of CD3+ T and CD3+CD4+ T cells, as well as CRP levels, were positively correlated with BMI in schizophrenia patients, but the mitochondrial lymphocyte counts of CD3+CD4+ T cells were negatively correlated with the language scale in the RBANS." (PMID 38235140, 2023). "After FDR adjustment (PFDR<0.05), we detected protective effects of four immunophenotypes on schizophrenia: naive CD4+%T cell (maturation stages of T cell panel), HLA DR on CD14−CD16− (monocyte panel), CD33dimHLA DR+CD11b−AC (myeloid cell panel) and activated & resting Treg % CD4 Treg (Treg panel)." (PMID 37582716, 2023). "Interestingly, the differences in granulocytes, natural killer cells, CD4+ T-cells, and CD8+ T-cells were most apparent in cohorts comprising patients with a diagnosis of schizophrenia, with cohorts including FEP patients characterized by weaker or null effects." (PMID 33646943, 2021). "A meta-analysis in drug-naïve patients with schizophrenia, reported increased numbers of total lymphocytes, T lymphocytes (CD3 positive), T helper cells (CD4 positive), and a higher ratio between T helper and T cytotoxic cells (CD4/CD8), but a reduced proportion of T lymphocytes." (PMID 28870209, 2017).
alveolitis (34 papers, 2009 to 2025). "An early CD4 T cell response promotes immune control, prevents neutrophil dysregulation, and leads to alveolitis with intact lung epithelial architecture." (PMID 40736456, 2025). "In contrast, concomitant immunity elicits early T cell recruitment to sites of infection, where CD4 T cells induce macrophage activation and disrupt neutrophil-driven lung pathology to elicit formation of alveolitis." (PMID 40736456, 2025). "Only one study investigated the presence of CD4 and CD8 in the BAL of SSc-ILD patients with alveolitis: the mean values of CD4 and CD8 were 43.9 ± 13.9% and 34.1 ± 15%, respectively." (PMID 36559035, 2022). "BAL cell differentials showed a lymphocytic (lymphocytes ≥ 20%) alveolitis in 8 (44%) patients with a majority of CD4/CD8 ratios > 3.5." (PMID 34063172, 2021). "BAL fluid analysis in cases of the drug induced alveolitis showed a predominance of CD4-positive lymphocytes allowing the authors to suggest that a cell mediated autoimmune response may be one of the factors responsible for sirolimus induced pulmonary toxicity." (PMID 22416975, 2012). "CD161 expression has been reported on 1.2% of CD4+ and 1.5% of CD8+ T cells from the BAL fluid of patients with hypersensitivity pneumonitis." (PMID 25906076, 2015). "High CD4/CD8 ratio, high intensity alveolitis (T-cell percentage > 28%) and elevated serum ACE levels were significantly more common in patients with specific cutaneous involvement (p < 0.01)." (PMID 23521826, 2013). "While the relatively small subset of CD4+ T cells found in the lung are infected in high frequencies, it has been reported that CD8+ T cells, present in high quantities during HIV-induced alveolitis, can also be infected." (PMID 19759830, 2009). "CD4+ T cell levels were non-significantly higher in patients with alveolitis, whereas glucocorticoid exposure was comparable in the two groups." (PMID 31776705, 2019). "In patients with fibrotic hypersensitivity pneumonitis, ozanimod alleviated CD3/CD28 induction of CD69, IL-4, and TNF in CD8, but not CD4 T cells." (PMID 40243992, 2025). "Imaging findings were suggestive of interstitial lung disease, with peripheral consolidations and mild ground glass opacities prompted pronchoalveolar lavage, which revealed a CD4/CD8 ratio of 0.9; antigen testing for hypersensitivity pneumonitis (which was initially suspected) was negative." (PMID 38398362, 2024).
anal carcinoma (33 papers, 2013 to 2025). "A 10-fold increase in HIV RNA viral load was associated with a higher risk of anal cancer (HR 1.31; 95% CI 1.08–1.59) in the partially adjusted model but the HR decreased to 1.12 (95% CI 0.90–1.39) after further controlling for CD4 count." (PMID 41311919, 2025). "Studies in North America and Europe have found nadir and lagged CD4 counts to be better predictors of anal cancer risk than current CD4 counts." (PMID 41311919, 2025). "A small retrospective cohort also identified a pretreatment CD4 count below 200 as a factor associated with poorer anal cancer control and increased treatment-related morbidity." (PMID 40606940, 2025). "When we included individuals with a single C21 ICD-10 code as patients with anal cancer, the association with CD4 count and HIV RNA viral load was similar to the main analysis." (PMID 41311919, 2025). "The risk of developing anal cancer seems to be particularly elevated among individuals with low CD4 counts or AIDS." (PMID 41311919, 2025). "It is considered that increased risk is not only the result of a low circulating CD4+ cells, because higher rates of anal cancer have been observed among HIV-infected individuals even when their CD4+ cell count is normal." (PMID 35645248, 2022). "The duration of immunodeficiency and viral replication appears to play an essential role in developing anal cancer, as the CD4 cell count and antiretroviral therapy have been associated with anal cancer." (PMID 35804810, 2022). "There was an association between a low CD4 count (< 200 cells/mm3) and rapid anal cancer progression in HIV-infected MSM." (PMID 34469465, 2021). "A cohort study from Swiss addressing the relationship between CD4+ T cell level and anal cancer risk suggested a rough estimate of the fraction of anal cancer." (PMID 25923768, 2015). "Beyond routine anal cancer screening, close monitoring of CD4 counts could help identify PWH at heightened risk of anal cancer, enabling targeted screening and prevention strategies." (PMID 41311919, 2025). "Lower CD4 counts were associated with an increased anal cancer risk in all models." (PMID 41311919, 2025). "In conclusion, lower CD4 counts were associated with an increased risk of anal cancer diagnosis." (PMID 41311919, 2025). "Anal cancer risk decreased significantly with higher time-updated CD4 cell count." (PMID 41074705, 2025). "Increased anal cancer risk has been associated with a lower CD4+ T-cell count (CD4)." (PMID 39339897, 2024). "Low CD4 cell count nadir was significantly associated with higher risk of anal cancer." (PMID 30362663, 2018). "Lower CD4 counts and, to a lesser extent, higher HIV RNA viral loads were associated with an increased anal cancer risk." (PMID 41311919, 2025). "At the start of follow-up, individuals who later developed incident anal cancer had lower CD4 counts and higher HIV RNA viral loads than individuals who did not develop anal cancer." (PMID 41311919, 2025). "The rate of anal cancer increased by 17% (HR: 1.17, 95% CI 1.04–1.31) per 100 CD4 cells/μL decrease, after controlling for HIV RNA viral load and the other factors." (PMID 41311919, 2025). "To address this gap, we examined the association of CD4 count and HIV RNA viral load with incident anal cancer among PWH in South Africa." (PMID 41311919, 2025). "While elevated anal cancer rates among PWH with low CD4 cell counts are well documented, the association between HIV RNA viral load and anal cancer risk is less well studied." (PMID 41311919, 2025). "We found that lower CD4 counts and, to a lesser extent, higher HIV RNA viral loads were associated with an increased risk of anal cancer diagnosis in this private-sector HIV disease management program." (PMID 41311919, 2025). "Low baseline CD4+ cell count and a low CD4+ nadir are both linked to a higher prevalence of SIL and a higher risk of anal cancer in PLHIV." (PMID 39274459, 2024).
anal carcinoma (continued). "Patients at risk of anal cancer, such as those who are HIV-positive, especially with the lower CD4 count, and MSM, would benefit with an earlier diagnosis if we considered the identification of HR-HPV infection before the emergence of the abnormal cells." (PMID 29975716, 2018). "For example, a 2012 study examined CD4 counts amongst HIV-positive patients undergoing chemotherapy for anal cancer and demonstrated median CD4 cell counts <300 suggesting ongoing active HIV infection." (PMID 27495294, 2016). "In contrast, a North American study found that while nadir and cumulative CD4 cell counts were strong predictors of anal cancer risk, adding HIV RNA viral load did not further improve the prediction." (PMID 41311919, 2025). "However, in the largest cohorts that evaluated CD4 count and survival outcomes in anal cancer patients with HIV-positive from 142 to 196 patients, they did not observe a negative impact on overall survival." (PMID 40842031, 2025). "There was some evidence of a higher risk of anal cancer among individuals with HIV RNA viral loads ≥1000 copies/mL than those with suppressed viral load (adjusted HR 1.98, 95% CI 1.00–3.89), after controlling for CD4 count." (PMID 41311919, 2025). "Maintaining high CD4 counts may contribute to anal cancer prevention among PWH in South Africa." (PMID 41311919, 2025). "Moreover, the combination of HPV16 L1 gene hypermethylation together with a low CD4 count in HIV-infected patients might be used as a biomarker for rapid progression to more severe lesions and anal cancer than those with a low methylation and high CD4 count." (PMID 34469465, 2021). "However, the analyses were often not adjusted for CD4 nadir, while it is associated both with the risk of anal cancer and ARV treatment initiated with a PI‐based regimen at treatment initiation nor adjusted for the whole ARV treatment history." (PMID 30362663, 2018). "However, PLWH on ART with good restoration of their CD4+ T cell count remain at increased risk of all cancers compared to the general population, including non-AIDS defining cancers (NADC) such as lung, liver, head and neck and anal carcinoma." (PMID 29443936, 2018). "However, these primary analyses did not adjust for CD4 count at treatment initiation and duration of CD4 count <200 cells/μl, known to be associated with the likelihood of receiving PI and the risk of anal cancer." (PMID 29202691, 2017). "Although some studies have reported that high HIV RNA viral loads are associated with increased anal cancer risk, and viral suppression on antiretroviral therapy (ART) with reduced risk, others suggest that these effects might be entirely mediated by CD4 count." (PMID 41311919, 2025). "CD4+ T cell function and infiltration into the sequenced non-recurrent anal cancer isolates, specifically, seem to be the main immune mediators that disappear in recurrence." (PMID 37177979, 2023). "We illustrated the method to evaluate the specific effect of protease inhibitors combined (or not) to other antiretroviral medications on the anal cancer risk in HIV-infected individuals, with CD4 cell count as time-dependent confounder." (PMID 29202691, 2017). "HIV-positive patients with anal cancer who received sulfonyl-containing HAART during definitive chemoradiotherapy demonstrated a significantly higher overall response rate at 6 months, independent of baseline CD4 count." (PMID 40842031, 2025).
Cachexia (33 papers, 2011 to 2026). Severe weight loss, wasting of muscle, loss of appetite, and general debility related to a chronic disease. "Nadir CD4+ T-cell count, cachexia and hemoglobin levels were associated with a high risk of mortality even after the first year of antiretroviral therapy." (PMID 25888439, 2015). "Majority of patients started ART at a late disease stage characterised by wasting syndrome, lower CD4 cells, and these were associated with higher mortality." (PMID 22973505, 2012). "Finally, both doses induced a drastic depletion of terminally differentiated CD4+ T cells (at day 45 after treatment) associated with the occurrence of a wasting syndrome characterized by weight loss and diarrhea." (PMID 23021024, 2012). "The authors further demonstrated that CD4+ T helper cells are the primary source of cachexia-related proinflammatory cytokines such as TNF-α." (PMID 41526343, 2026). "A study show an immune cell subset that promotes protection from cachexia, for example, CD4+ can relieve the symptoms of cachexia and the decrease of CD4+ will aggravate the symptoms of cancer cachexia." (PMID 36105371, 2022). "We found that a transfer of exclusively CD4+CD44−Foxp3GFP− Tn cells from EpTCRmini mice to lymphopenic EpTCRαk/o recipients resulted in lethal cachexia in <8 weeks, demonstrating that a single AbEp complex activated autologous CD4+ Tn cells." (PMID 33139845, 2021). "Lower body weight (cachexia or wasting syndrome) and lower CD4 count are proxy measures of advanced disease stage." (PMID 22973505, 2012). "As a result, this may be useful in limiting the participation of people with a low CD4+ count, advanced disease stages, or wasting syndrome to minimize their confounding effect on weight gaining pattern analysis." (PMID 37531412, 2023). "In addition to the cachexia-associated loss of CD3+ T cells, this analysis demonstrated the depletion of CD8+ T cells, CD4+Foxp3− T cells, and NK cells." (PMID 27829137, 2016). "The fact that similar associations between CD4 cell counts and wasting exist in HIV-/TB suggests that TB may contribute to the wasting syndrome commonly found in co-infected patients, as well as contributing to CD4 cell depletion." (PMID 24358268, 2013). "Another study reported that the numbers of CD3+, CD4+ and CD8+ T cells gradually decreased during cachexia progression in C26 tumor-bearing mice." (PMID 33017424, 2020). "Further research showed that CD4 T cells were markedly increased and they ectopically produced different cachexia cytokines in different non-immune organs." (PMID 32139788, 2020). "An age-dependent association between the CD4/CD8 ratio and frailty has been noted in patients with HIV, which are also prone to develop cachexia; however, this seemed not to be the case in our mouse models of cancer cachexia." (PMID 35008253, 2021). "However, ablation of individual cell subsets such as CD4+ T cells or macrophages, or of TNF-α did not prevent a wasting phenotype associated with cachexia." (PMID 32676079, 2020). "Because TNF-α and possibly other cytokines contributed to cachexia following i.v. injection of iC9-CD19.ζ-MC-modified T cells, we sought to determine if the selection of CD8+ T cells (or depletion of CD4+ cells) could lessen the toxicity while preserving antitumor activity." (PMID 30816327, 2019). "While WT cells successfully induced wasting syndromes in the recipients, PP4-deficient CD4+CD45RBhigh cells failed to do so; these results could potentially be linked with the hypo-proliferation or reduced Th17 polarization of PP4-deficient T cells." (PMID 24904742, 2014).
cryptosporidiosis (33 papers, 2012 to 2025). Intestinal infection with organisms of the genus Cryptosporidium. "Immunocompromised individuals are at the highest risk of morbidity and mortality due to chronic cryptosporidiosis, largely due to the ineffectiveness of anti-Cryptosporidium treatment in patients with low CD4+ cell counts." (PMID 40005709, 2025). "Studies indicate that individuals with a cluster of differentiation 4 (CD4) count below 200 cells/mm3 are at increased risk for severe cryptosporidiosis, often resulting in prolonged gastrointestinal symptoms and complications." (PMID 40981154, 2025). "Consistent with previous studies examining the host immune response to Cryptosporidium infection, mice deficient in CD4+ or CD8+ lymphocytes showed a longer course of infection with C. mortiferum than immunocompetent individuals." (PMID 37454101, 2023). "In HIV patients, CD4+T cell counts <100 cells/mm3 were associated with susceptibility to the Cryptosporidium infection." (PMID 36851577, 2023). "Future studies should be carried out to overcome some limitations of this study, such as the small sample size and, therefore, the impossibility of associating cryptosporidiosis with the CD4 count and symptoms of the patients." (PMID 33805766, 2021). "Other research studyby Paboriboune et al56 showed that a relatively good effect size with RR = 1.422 (95% CI =1.089-1.858) and a weight of 31.62% indicated the risk of cryptosporidiosis againstlow CD4+ T-lymphocyte counts." (PMID 32037854, 2020). "CD4+ cells count lower than 200cells/mm3 have been associated with both cryptosporidiosis and cyclosporiasis." (PMID 30369995, 2018). "Though there are increasing reports on the prevalence of cryptosporidiosis and its association with depleted CD4+ cells among HIV patients in Ghana, little is known about its transmission risk factors." (PMID 30369995, 2018). "It has been well documented in previous studies that patients having lower CD4 count are at higher risk of cryptosporidiosis." (PMID 26981284, 2016). "In our study, CD4 count among RT patients was not as low as that in HIV positive patients with cryptosporidiosis, suggesting that depletion of immune cells and factors other than CD4 count is responsible for susceptibility to cryptosporidiosis in RT patients." (PMID 26981284, 2016). "In addition, individuals with CD4 counts below 200 cells/mm3 are at greater risk for severe and persistent cryptosporidiosis." (PMID 40981154, 2025). "Individuals with low CD4 counts are at risk for Cryptosporidium infection due to immunosuppression." (PMID 40981154, 2025). "Also, there were statistical differences between the diarrhea, CD4 < 200 cells/mL, and antiretroviral therapy risk factors with Cryptosporidiosis." (PMID 32351207, 2020). "Similarly, the association of Cryptosporidium infection with diarrheal status was found to be statistically significant in patients with a CD4 level < 200 cells/μl in which the parasite was more likely to be detected in those who had chronic diarrhea." (PMID 27165271, 2016). "To date, the only FDA-approved anti-Cryptosporidium drugs available rely on the host’s ability to produce CD4+ cells, which is why chronic cryptosporidiosis remains a real threat to immunocompromised patients." (PMID 40005709, 2025). "Suppression of CD4+ T cells has been shown to be a key factor in the persistence of cryptosporidiosis in mammals." (PMID 39339972, 2024). "Covariates describing cryptosporidiosis‐associated diarrhea severity (e.g., number of diarrhea episodes, diarrhea grade) or HIV infection (e.g., viral load, CD4+ T cell count) were evaluated." (PMID 38164114, 2024). "IFN-γ producing CD4+ T IELs provide an efficient and a long-term protection against cryptosporidiosis while intraepithelial type 1 innate lymphoid cells limits pathogen spreading during early stages of infection in immunodeficient individuals." (PMID 37744354, 2023).